COL6A1 (collagen type VI alpha 1 chain)
Diseases named in the same sentence as COL6A1 in open-access papers (continued):
Sharing a sentence is not in itself a finding about the gene and the disease.
prostate carcinoma (7 papers, 2008 to 2023). A carcinoma that arises from epithelial cells of the prostate gland. "Overexpression of COL6A1 was associated with accelerated S phase entry and elevated vitality in prostate cancer cells." (PMID 25895032, 2015). "The collagen proteins play a role in maintaining the integrity of various tissues and COL6A1 was also downregulated in prostate cancer, colorectal cancer and ovarian cancer." (PMID 37371512, 2023). "According to a study that applied comparative urine proteomics profiling from prostate cancer patients, COL6A1 protein had a highly confirmed involvement in prostate cancer as well." (PMID 35884419, 2022). "In a mouse model of prostate cancer, COL6A1 influenced the growth of tumors from nude mice subcutaneously injected with LNCaP cells." (PMID 25895032, 2015). "Taken together, these data suggest an important role of COL6A1 in the molecular etiology of castration-resistant prostate cancer, and support the potential use of COL6A1 in CRPC therapy." (PMID 25895032, 2015). "Together, these results demonstrated that COL6A1 might act as an oncogene, which could promote prostate cancer proliferation." (PMID 25895032, 2015). "COL6A1 that is synthesized and secreted by prostate cancer cells may play a role in or act like a marker for the transformation from ADPC to CRPC." (PMID 25895032, 2015). "COL6A1 may play an important role in the progression of prostate cancer." (PMID 25895032, 2015). "To further clarify the role of COL6A1 in prostate cancer, we constructed overexpression vectors containing an open reading frame (ORF) of COL6A1 and used lentivirus to introduce the vectors into LNCaP cells which barely expressed COL6A1." (PMID 25895032, 2015).
glioblastoma (5 papers, 2018 to 2024). The most malignant astrocytic tumor (WHO grade IV). "Higher expression of COL6A1 has also been observed in glioblastoma multiforme compared to normal brain tissues and was associated with a poor prognosis." (PMID 37987316, 2023). "Previous studies have indicated that COL6A1 is upregulated in several malignancies, including glioblastoma and astrocytoma 25, 26, although they failed to investigate the underlying mechanism(s)." (PMID 33391546, 2021).
keloid (5 papers, 2014 to 2025). An irregularly shaped, elevated mark on the skin caused by deposits of excessive amounts of collagen during wound healing. "Patients suffering from collagen VI related myopathies caused by mutations in COL6A1, COL6A2 and COL6A3 often also display skin abnormalities, like formation of keloids or “cigarette paper” scars, dry skin, striae rubrae and keratosis pilaris (follicular keratosis)." (PMID 25158062, 2014). "We clustered collagen gene expression in keloids and lymphedema and found that keloid tissue tended to have higher expression of COL3A1, COL1A2, COL1A1, COL6A1, and COL5A1 than did the ML and SL groups." (PMID 40742741, 2025). "They determined that only 25 common dysregulated genes were in keloids in 7 studies where collagen, type I, alpha 1 (COL1A1); collagen, type I, alpha 2 (COL1A2); collagen, type V, alpha 2 (COL5A2); and collagen, type VI, alpha 1 (COL6A1) were systematically upregulated." (PMID 33860039, 2021). "However, in contrast to the hypertrophic scars or keloids occurring in patients with a collagen VI myopathies, we did not observe such disturbed wound healing in the Col6a1 null mice." (PMID 25158062, 2014).
lymph node metastasis (5 papers, 2018 to 2025). "The low expression of the proteins LTA4H, PGK1, NDRG1, COL6A1, and ITGAV in the saliva samples was associated with lymph node metastasis and advanced clinical staging (crosstabulation and chi-square test, P value < 0.05)." (PMID 30185791, 2018). "Interestingly, SRM-MS analysis showed CSTB, LTA4H, PGK1, COL6A1, ITGAV, and NDRG1 were significantly downregulated in patients with lymph node metastasis." (PMID 30185791, 2018). "In summary, a sensitive electrochemical biosensor was successfully developed to detect and quantify CSTB, LTA4H, and COL6A1 biomarkers in noninvasive saliva samples from OSCC patients, with and without lymph node metastasis." (PMID 40728373, 2025).
Alzheimer disease (4 papers, 2018 to 2023). A progressive, neurodegenerative disease characterized by loss of function and death of nerve cells in several areas of the brain leading to loss of cognitive function such as memory and language. "A recent study has implicated ColVI in Alzheimer’s disease (AD); in this case, both mRNA and protein levels of Col6a1 were increased in hippocampus of a mouse model of AD66." (PMID 37903805, 2023). "The other ECM protein COL6A1 that targeted by miR-1233-3p, was mostly found on the close periphery of the cell surface and considered a neuroprotective role against the toxicity of amyloid-β peptides in Alzheimer’s disease mouse models." (PMID 36204112, 2022). "Given that METH can often lead to pathological changes similar to those seen in Alzheimer’s disease and Parkinson’s disease, the role of ITGA7 and COL6A1 in METH-induced neurotoxicity warrants deeper understanding." (PMID 36204112, 2022). "Higher levels of the Col6a1 transcript and protein were observed in hippocampal neurons of mice expressing mutant human APP, and a higher expression of COL6A1, COL6A2 and COL6A3 mRNA was also detected in the dentate gyrus of Alzheimer's disease patients compared with cognitively normal controls." (PMID 29728408, 2018).
astrocytoma (4 papers, 2010 to 2022). "High COL6A1 expression levels were observed in astrocytoma of different malignancy grades, especially in higher grade tumors associated with poor prognosis." (PMID 36076905, 2022). "COL6A1, which is a conservative gene/protein in vertebrates and is present in all connective tissues, was recently found to be differentially expressed in astrocytomas." (PMID 26317545, 2015).
clear cell renal cell carcinoma (4 papers, 2015 to 2023). "In this study, we investigated the potential role of the COL6A1 gene, which encodes the α1 polypeptide of collagen VI, in the biological functions involved in the progression and outcome of clear cell renal cell carcinoma (ccRCC)." (PMID 26317545, 2015). "For instance, IGF2BP3 enhanced the proliferative activity of clear cell renal cell cancer cells by increasing the expression of cyclin-dependent kinase 4, collagen type VI alpha 1 chain, laminin subunit alpha 5, and fibronectin 1 in an m6A-dependent manner." (PMID 34621671, 2021). "In clear cell renal cell carcinoma, the complex of IGF2BP3/lncRNA DMDRMR selectively interacts with their m6A-modified co-targets (including CDK4, COL6A1, LAMA5, and FN1) to promote cell proliferation." (PMID 37280679, 2023).
COVID-19 (4 papers, 2020 to 2023). A disease caused by infection with severe acute respiratory syndrome coronavirus 2. "The genes associated with EDS or COVID-19 severity are distributed on all chromosomes (except for Y and 8, 13, 16, 20 for COVID-19) with clusters at 2q32.2 (COL5A2/COL3), 3p24.1 (SCN5/10/11A), 11q23.3 (SCN2/4B), and 21q22.3 (COL6A1/A2) for EDS and at 3p22.2 (CCR1/5-CXCR6) for COVID-19 (column L)." (PMID 37504295, 2023).
Down syndrome (4 papers, 2019 to 2024). "Analysis of rare segmental trisomies of chromosome 21 suggested that duplication of DSCAM and the contiguous COL6A1 and COL6A2 genes may cause septal abnormalities and other Down Syndrome-related CHD lesions, including BAV." (PMID 37961530, 2023). "In a cohort of patients with Down syndrome and AVSD, variants with the highest probability of being damaging in cases compared to Down syndrome patients without cardiac defects were in the VEGF-A pathway genes COL6A1, COL6A2, CRELD1, FBLN2, FRZB, and GATA5." (PMID 31888141, 2019).
lung fibrosis (4 papers, 2020 to 2025). "In keeping with this, colonic macrophages from ILC-depleted mice showed an increase in Col6a1, Col6a2, and Col6a3 transcripts that together form trimers that make up collagen type VI, previously shown to promote myofibroblast activation in the context of lung fibrosis." (PMID 32640223, 2020). "Taken together, the elevated levels of POSTN, THBS2, COL6A1, and LOXL1 may contribute to the development of pulmonary fibrosis, similar to what is seen in IPF, thus connecting fibrosis to inflammation in DM-ILD." (PMID 37928522, 2023).
ovarian carcinoma (4 papers, 2015 to 2023). A malignant neoplasm originating from the surface ovarian epithelium. "In ovarian cancer cells, COL6A1 has been identified as an effector gene that promotes invasion and metastasis." (PMID 38031074, 2023).
Arthritis (3 papers, 2018 to 2024). Inflammation of a joint. "To elucidate the role of synovial fibroblast OSM signaling in arthritis, we generated Col6a1-Cre Osmr-floxed mice (hereafter Osmr∆Fibro mice) in which OSMR is specifically deleted in synovial fibroblasts in joints." (PMID 39080781, 2024). "Col6a1-Bmal1−/− mice showed enhanced localised inflammation after induction of arthritis." (PMID 30612576, 2019).
colitis (3 papers, 2022 to 2023). Inflammation of the colon. "We have shown in the past that deletion of immune-related genes, such as Ikk2 and Myd88 in Col6a1+ fibroblasts, results in reduced spontaneous and/or colitis-associated carcinogenesis." (PMID 38203319, 2023). "In this study, we explored the properties and pathophysiological role of Col6a1+ and Col6a1− CAFs in mouse AOM/DSS-induced colitis-associated carcinogenesis, as we have previously shown that the two subsets represent distinct fibroblast populations in the colon." (PMID 38203319, 2023). "For this reason, we crossed Il1r1f/f and p55f/f mice with the Col6a1Cre strain to specifically inhibit the IL-1R and TNFR pathways in Col6a1+ IMCs and then subjected the mice to the AOM/DSS protocol of colitis-associated carcinogenesis." (PMID 38203319, 2023).
colorectal cancer (3 papers, 2019 to 2023). A primary or metastatic malignant neoplasm that affects the colon or rectum. "Based on the immunohistochemical results from the HPA database, we studied the protein expression of COL6A1/2/3 in colorectal cancer tissues." (PMID 36167487, 2022). "Besides, the CCLE database was used to show the expression of COL6A1/2/3 in colorectal cancer cell lines." (PMID 36167487, 2022).
emphysema (3 papers, 2014 to 2023). "Our preliminary data also found a greatly reduced DNA methylation in the COL6A1 gene from lung tissue with both emphysema and adenocarcinoma as compared to that of adjacent normal section from the same patient (data not shown)." (PMID 25176343, 2014). "We identified a series of significant pathways, including BCR signaling pathway, ECM-related pathways, NF-κB and TGF-β signaling pathways, and several hub genes (i.e. CD19, BLK, MS4A1, POU2AF1, and COL6A1) that may be involved in the emphysema phenotype of COPD." (PMID 33535173, 2021). "KEGG pathway analysis showed upregulation of the term “ECM-receptor interaction”, which includes integrin subunit alpha 3 (ITGA3), collagen type VI α1 chain (COL6A1), and heparan sulfate proteoglycan 2 (HSPG2) in the non-emphysema subgroup." (PMID 38203236, 2023). "In our study, COL6A1 and EMILIN1, two genes involved in ECM organization, were also enriched in emphysema, and therefore their function in emphysema and COPD merits further research." (PMID 33535173, 2021).
fibrosis (3 papers, 2014 to 2020). the formation of excess fibrous connective tissue in an organ or tissue in a reparative or reactive process. "Expression of collagen VI chains is regulated in both skin wounds and bleomycin-induced fibrosis and the collagen VI α3 chain is proteolytically processed in both wild type and Col6a1 null mice." (PMID 25158062, 2014). "We confirmed that COL6A1/2/3 depletion in myofibroblasts significantly reduced chemotaxis of the myeloid cell line THP-1 toward myofibroblast conditioned media, suggesting collagen VI may play an important role in promoting immune cell recruitment in localized fibrosis." (PMID 32759223, 2020).
keratoconus (3 papers, 2020 to 2023). A degenerative, structural disorder of the eye, characterized by a cone-shaped protrusion of the cornea. "The reported lead keratoconus GWAS variant (rs142493024, p-value = 9 × 10−12) at locus 35 is a low-frequency variant missing from summary statistics, along with the other intronic COL6A1 variants forming one of four CS delineated at CRF locus 115 by DAP-G (cs1), SuSiE (cs1), and FINEMAP (cs4)." (PMID 37621707, 2023).
melanoma (3 papers, 2019 to 2023). A malignant, usually aggressive tumor composed of atypical, neoplastic melanocytes. "Interestingly, several of these AhR‐associated genes have been involved in the aggressiveness of melanoma or other cancers and have been associated with a poor prognosis (ABCG2, COL1A1, COL6A1, COL6A2, TGFBI)." (PMID 36305167, 2022). "First, high level and activity of AhR mediates the invasive/dedifferentiated phenotype of melanoma through the direct regulation of the expression of many genes involved in invasion (COL1A1, COL6A1, COL6A2, CYR61, STC2...) and dedifferentiation phenotypes (CCL2, NTM, NUAK2, SOX9, ABCG2...)." (PMID 36305167, 2022).
metastatic tumor (3 papers, 2011 to 2025). "Expression of COL2A1, COL11A1, COL6A1, COL6A2 and LUM tended to be higher in primary/metastatic tumor than in normal tissue." (PMID 40927672, 2025).
muscle disorders (3 papers, 2013 to 2019). "Collagen VI-related myopathies are a spectrum of muscular diseases with features of muscle weakness and atrophy, multiple contractures of joints, distal hyperextensibility, severe respiratory dysfunction and cutaneous alterations, attributable to mutations in the COL6A1, COL6A2, and COL6A3 genes." (PMID 30808312, 2019).
myocardial infarction (3 papers, 2017 to 2025). Gross necrosis of the myocardium, as a result of interruption of the blood supply to the area, as in coronary thrombosis. "In acute myocardial infarction mouse models, five genes (Ptpn6, Csf1r, Col6a1, Cyba, and Map3k14) have been implicated in the acute myocardial infarction pathway by regulating DNA methylation, suggesting their potential as early methylated biomarkers for clinical diagnosis." (PMID 40428388, 2025). "Additionally, post myocardial infarction cardiac function and remodeling is improved in mice lacking the COL6A1 gene relative to wild type controls." (PMID 29367553, 2017). "Finally, Col6a1, which was correlated with lung weight with borderline significance (r = 0.451, p = 7.95e−06, BH adjusted p = 0.0549) has previously been shown, when absent, to be protective following myocardial infarction by limiting infarct size, apoptosis, aberrant remodeling and fibrosis." (PMID 31417910, 2019).
osteoarthritis (3 papers, 2012 to 2023). A noninflammatory degenerative joint disease occurring chiefly in older persons, characterized by degeneration of the articular cartilage, hypertrophy of bone at the margins and changes in the synovial membrane. "Moreover, COL5A2 and COL6A1 were also demonstrated as upregulated genes associated with a pathological process of subchondral bone in osteoarthritis." (PMID 35831853, 2022). "Further analysis of these enriched pathways in injurious hydrostatic pressure highlighted differential expression of several genes known to be involved in osteoarthritis, such as Fgf2, Ep300, Ngf, Adam9, Igfbp3, Sox9, Comp, Col6a1, Col6a2 and Col11a1." (PMID 38144567, 2023). "In addition, several genes known to play a key role in progression of osteoarthritis (e.g., Fgf2, Ep300, Ngf, Adam9, Igfbp3, Sox9, Comp, Col6a1, Col6a2 and Col11a1) were modulated in our injurious hydrostatic pressure hip cap datasets, thereby validating this approach." (PMID 38144567, 2023).
adenoma (2 papers, 2023 to 2024). A neoplasm arising from the epithelium. "Other frequently enriched genes in adenoma include collagen family members such as COL6A1, COL6A2, and COL6A3." (PMID 39408697, 2024). "We found that Col6a1+ cells partly maintain their homeostatic features during adenoma development, while their activation is characterized by the acquisition of a distinct proangiogenic signature associated with their initial perivascular location." (PMID 38203319, 2023).
atherosclerosis (2 papers, 2020 to 2022). A disease characterized by the build-up of fatty material and calcium deposition in the arterial wall resulting in partial or complete occlusion of the arterial lumen. "Increased CD4+ T cell function is associated with worsening of experimental atherosclerosis, which we observed in the male COL6A1-immunized mice." (PMID 32373127, 2020). "Importantly, the report suggests that exaggerated immune challenges in female mice can result in pathologic responses to COL6A1 associated with the severity of atherosclerosis." (PMID 32373127, 2020). "Previous findings clearly indicate that COL6A1, in addition to the structural properties, also displays pro-angiogenic action, including endothelial cell proliferation, migration and survival, and its higher expression is associated with increased risk of hypertension and atherosclerosis." (PMID 36428375, 2022). "It is present in advanced lesions and identified as a specific autoantigen in atherosclerosis associated with experimental autoimmunity, supporting the notion that chronic inflammatory conditions lead to the generation of self-reactive immune responses to COL6A1." (PMID 32373127, 2020). "There was differential effect on atherosclerosis in mice immunized with COL6A1, wherein female mice had significantly reduced while male mice had significantly increased aortic atherosclerosis." (PMID 32373127, 2020). "On the other hand, female mice immunized with COL6A1 peptide had significantly reduced atherosclerosis whereas male mice had significantly increased atherosclerosis, associated with differential immune profiles." (PMID 32373127, 2020). "On the other hand, immunization with the peptide common to majority of female and male patients, COL6A1, had divergent effects on atherosclerosis." (PMID 32373127, 2020). "Altering self-reactive immune responses to COL6A1 in apoE–/– mice resulted in differential effects on atherosclerosis burden with sex as a determinant of outcome." (PMID 32373127, 2020). "It remains unclear how COL6A1 becomes a target of self-reactive immune responses in atherosclerosis." (PMID 32373127, 2020). "Effector T cell function that exacerbates atherosclerosis is attributed in part to IFN-γ, which concur with our observation that COL6A1 immunized male mice had increased CD4+ EM T cells and CD4+IFN-γ+ T cells." (PMID 32373127, 2020).
autoimmune disease (2 papers, 2014 to 2025). A disorder resulting from loss of function or tissue destruction of an organ or multiple organs, arising from humoral or cellular immune responses of the individual to their own tissue constituents. "COL6A1 has previously been linked to muscle regeneration and associated with other myopathies, whereas LCP1 is a bundle protein linking actin filaments together and associated with autoimmune disease." (PMID 24920607, 2014). "COL6A1 (Collagen Type VI Alpha 1 Chain) is a component of the extracellular matrix found in oral mucosa and several other tissues and may therefore be clinically relevant to this toxicity, but has not been previously reported in mucositis or autoimmune disease." (PMID 40449958, 2025).
breast tumors (2 papers, 2016 to 2023). "Also, the collagen VI (COL6A1)/collagen I (COL1A1) mRNA ratio (COL6A1/COL1A1) was significantly higher in basal than luminal A breast tumours." (PMID 27725631, 2016).
colon cancer (2 papers, 2022 to 2023). "Initially, we assessed the colony formation potential of Caco-2 colon cancer cells grown on top of either Col6a1+ or Col6a1− IMCs." (PMID 38203319, 2023). "We isolated fresh colonic Col6a1+ and Col6a1− IMCs through FACS sorting and co-injected them with MC38 colon cancer cells subcutaneously in the flanks of C57/Bl6 wild-type mice." (PMID 38203319, 2023).